IL6 (interleukin 6)
Diseases named in the same sentence as IL6 in open-access papers (continued):
Sharing a sentence is not in itself a finding about the gene and the disease.
tumor (continued). "Thus, combined HCC-CCA originates from hepatic progenitor cells and, in the context of an inflammatory microenvironment, senescent-associated IL-6 plays an important role in tumor progression via IL-6 trans-signaling." (PMID 38275386, 2023). "The results showed that TG-EXO were co-cultured with macrophages could promote macrophages to secrete IL-6 and induce them to transform into tumor-associated M2 macrophages." (PMID 37151385, 2023). "In addition, IL-6 protects tumor cells from DNA damage, oxidative stress and apoptosis caused by treatment by promoting repair and inducing anti apoptosis pathway, which has anti-cancer effect." (PMID 36845384, 2023). "Using the system to deliver a combinatorial gene of interleukin 6 short hairpin RNA (IL-6 shRNA) and CD19 CAR, they successfully transformed T-cells into IL-6 downregulated CAR-T-cells, which killed leukemic tumor cells with high CD19 expression while reducing the CRS caused by IL-6." (PMID 37388769, 2023). "IL-6 can induce tumor angiogenesis, regulate genes associated with the cell cycle, promote tumor proliferation, and regulate the local inflammatory environment to promote the tumor’s development." (PMID 37719006, 2023). "The combination of both nanoformulations transformed the ‘cold’ TME into a ‘hot’ one, supported by increased numbers of CD8+ T cells, CD4+ T cells, dendritic cells, IFN-γ, TNF-α, and IL-12 and reduced numbers of MDSCs, Tregs, tumor-associated macrophages (M2), IL-4, IL-6, and IL-10." (PMID 37600822, 2023). "Mechanistically, miR-25–3p and miR-92a-3p stimulated the secretion of pro-inflammatory cytokine IL-6 from tumor-associated TAM in a TLR7/8-dependent manner, in turn promoting LPS cell proliferation, invasion, and metastasis via this interaction with the surrounding microenvironment." (PMID 36979391, 2023). "This may be due to in malnourished patients with cancer tumor cell-mediated cytokines such as IL-1, Il-6, and (TNF-α) cause hemolysis, lowering Hgb levels." (PMID 36869395, 2023). "The “seed and soil” theory postulates that tumor cells produce several tumor-associated factors, including interleukins (IL-1β, IL-6, IL-8, IL-11, IL-17), macrophage inflammatory protein 1α, TNFα, parathyroid hormone-releasing protein (PTHrP), and prostaglandin E (PGE2)." (PMID 36294305, 2022). "A potential mediator limiting the impacts of weight loss on tumor progression after VSG was elevated IL-6, which upregulates the checkpoint ligand, programmed death ligand 1 (PD-L1) on myeloid and non-immune cells, and reduced CD8+T cell content in tumors uniquely in VSG-treated mice." (PMID 35775614, 2022). "Notably, the transplanted TC-1 cells were capable of producing IL-6, underlining the importance of endogenous IL-6 on immune and stromal cells in the promotion of tumor growth." (PMID 36405719, 2022). "M2 macrophage behaviour exists more heterogeneously and can be triggered by IL-4 or IL-13, IL1-β, TGF-β, IL-6, phagocytosis of apoptotic cells, or association with a tumour microenvironment, respectively, generating M2a, M2b, M2c, M2f, and tumour-associated macrophages (TAM)." (PMID 36254592, 2022). "Likewise, IL6 is found in diverse TMEs and has been linked to tumor development and therapy resistance in various cancer entities via stimulating immune suppressive signals." (PMID 35892641, 2022). "We found that memantine treatment triggered spleen IL-6 production that might evoke immune response in mice and could be the underlying reason for decreased tumor volumes." (PMID 36326318, 2022). "The C-reactive protein (CRP) is produced by hepatocytes as a systemic response to cytokine stimulation (particularly interleukin-6) from tumor microenvironment leukocytes, and has been associated with progressive disease and relatively poor survival in patients with different malignancies." (PMID 35562926, 2022).
tumor (continued). "Interestingly, patients with TNBC showed increased presence of tumor associated macrophages and higher expression levels of IL-6 after surgery." (PMID 35163731, 2022). "Increased TNF-α signaling enhances the pro-oncogenic signaling pathways in epithelial cells through the Wnt/β-catenin pathway and NF-kB pathways, exacerbating the effects of proinflammatory cytokines in cancer-associated inflammation, especially IL-1β and IL-6, and accelerating tumor growth." (PMID 35884974, 2022). "Furthermore, a possible role of mTOR inhibitors in preventing and/or reversing tumor-associated cachexia through restoration of autophagy or reduction of IL-6 levels has also been demonstrated." (PMID 35805003, 2022). "Interestingly, the components of PFPE, 3-carene and pellitorine cause tumor regression by inhibiting CXCL7 production mediated by the activator IL-6." (PMID 35837284, 2022). "However, another research revealed that the high expression level of IL-6 is linked to low tumor burden and low proliferation scores in MM." (PMID 35958625, 2022). "Growth factors (G-CSF and granulocyte-macrophage colony-stimulating factor (GM-CSF)) and inflammatory cytokines (IL-6, IL-1β, and IL-17) produced by tumour cells, tumour-associated stromal cells, and tumour-infiltrating leukocytes (including T cells) can modulate haematopoiesis." (PMID 35860278, 2022). "Thus, elevated IL-6 levels are associated with more severe tumor stages, tumor invasion, and metastasis." (PMID 35892729, 2022). "Since IL-6 concentration in the serum of patients is associated with advanced tumor stage and overall survival, it may be used as a biomarker for preoperative assessment of prognosis." (PMID 35965509, 2022). "Moreover, interleukin-6 (IL-6) has been associated with the enrichment of immunosuppressive MDSCs in several tumor types." (PMID 35205742, 2022). "And a positive association between IL-6 levels and myeloid-derived suppressor cells, M2 macrophages and regulator T cells was also seen in tumor samples, which may result in an inferior response to ICIs." (PMID 35550592, 2022). "IL-6 is associated with aggressive and invasive tumor types." (PMID 35740551, 2022). "IL-9R-deficient tumor-bearing mice exhibited lower serum IL-6 level than WT mice." (PMID 35778404, 2022). "Obesity-induced adipose tissue inflammation may be a driver of cancer risk, and certain adipokines (e.g., CCL2, VEGF, IL-6, and IL-8) act as chemotherapy inducers that enhance tumor cell migration and support metastasis." (PMID 35379822, 2022). "Furthermore, S. mutans infection was associated with higher IL-6 expression and enhanced recruitment of MDSCs in the 4NQO-induced tumor model." (PMID 36186905, 2022). "In addition, key autophagy protein inhibition seems to play an important role in the protective effects of RT on tumor-induced muscle atrophy since it is directly associated with persistent IL-6 production and phosphorylation of STAT3." (PMID 35847939, 2022). "The IL-6/STAT3 pathway activation has been implicated in microbiome-induced tumor progression." (PMID 36186905, 2022). "As tumour cells in experimental CRC lose IL-6R expression and become susceptible to IL-6 trans-signalling via the soluble IL-6R,15 our findings underlined that Th9 cells may regulate tumour growth via IL-6 trans-signalling." (PMID 35793807, 2022). "During inflammation, IL-6 induces free radicals causing a DNA damage, favouring tumour initiation." (PMID 35793807, 2022). "Indeed, GBM tends to induce an immunosuppressed TME enriched in immunosuppressive chemokines (eg, TGFβ, IL10, IL6) secreted by tumor cells, microglia and tumor-associated macrophages (TAMs)." (PMID 36212741, 2022). "The effects of RFA to the tumor microenvironment could be linked to the activation of IL-6/HGF/c-Met pathway which produce downstream angiogenesis and VEGF production." (PMID 35710408, 2022).
tumor (continued). "As IL-6 is a key player in cytokine release syndrome as well as being implicated in enhancing tumour progression, such molecule designs could reduce side effects and cytotoxicity observed with previous TCEs and widen their therapeutic windows." (PMID 36439165, 2022). "Additionally, tumor derived IL-6 has been implicated as a potential inducer of autophagy in patients with lung and gastrointestinal cancers." (PMID 35743911, 2022). "These signals promote the activation of dendritic cells (DCs) and, as a result, the release of pro-inflammatory cytokines such as IL-1β, IL-6, IL-12, and TNFα, and facilitate the engulfing of dying cancer cells following tumour-associated antigen (TAA) presentation to the T cells." (PMID 36140243, 2022). "Tumor-associated macrophages facilitate the PD-L1 expression in GC via IL-6 and TNF-α signals." (PMID 35719369, 2022). "Indeed, experimental data indicate that elevated levels of interleukin 6 (IL-6), a pro-inflammatory pleiotropic cytokine, are associated with aggressive tumor behavior in UCB." (PMID 34023914, 2022). "Additionally, high NLR has been associated with elevated infiltration of tumour-associated macrophages in the tumour microenvironment and elevated circulating cytokines (IL-1ra, IL-6, IL-7, IL-8, IL-9, IL-12, IFN-γ, IP10, MCP-1, MIP-1β, and PDGF-BB)." (PMID 36077723, 2022). "In addition, tumor necrosis factor (TNF) and interleukin-6 (IL-6) were found to be autophagy inducers that are associated with carcinogenesis and tumor progression." (PMID 36230955, 2022). "The IL-6 level in HCC patients is closely linked to tumor progression and relapse, since IL-6 could induce myeloid-derived suppressor cells to inhibit T-cell immunity and enhance HCC progression." (PMID 36142683, 2022). "Especially in the early stages of colorectal PM, a major pattern of chronic inflammation represented by a tumor microenvironment rich in TAM2 with upregulation of IL-6 and rewiring of signaling pathways linked to plasticity, stemness and metabolism has been observed." (PMID 35912189, 2022). "Th2 cell was proposed to promote tumor progression through the secretion of cytokines interleukin (IL)‐4, IL‐6, IL‐10, and IL‐13 to activate tumor‐associated M2 macrophages, and which was found to be a risk factor of male patients in SARC, LUAD, KIRP, PAAD, KIRC, and LIHC (HR > 1, Wald P < 0.05)." (PMID 35229456, 2022). "In contrast, we observed a significant decrease in IL5, IL10, IL13, and IL6 levels, which are typically associated with tumor-promoting type 2 immune responses, which are known to support tumor growth, metastatic dissemination, and tumor evasion of immune surveillance." (PMID 35715953, 2022). "Interleukin-6 level is linked with MM severity and tumor cell mass." (PMID 36685193, 2022). "Interestingly, the tumor‐promoting effect of IL‐6 is inhibited by the knockdown of the gene encoding 6‐phoshofructo‐2‐kinase/fructose‐2,6‐bisphosphatase‐3." (PMID 35791509, 2022). "Furthermore, tumor-associated macrophages undergo “M2 polarization” by secreting IL-6 to promote PI3K/AKT phosphorylation." (PMID 36627890, 2022). "Therefore, our findings revealed that apoptosis in “inflammation–atypical hyperplasia–cancer” process was correlated with IL-6/STAT3 signaling pathway in CRC-associated tumor tissues." (PMID 35946886, 2022). "Also, it was found that Th17 cell count was positively related to the expression of IL-6, IL-17, and IL-1β cytokines and negatively associated with an increase in the number of metastatic lymph nodes and tumor cell angiogenesis." (PMID 35248028, 2022). "Therefore, the progress of DLBCL is plausibly associated with the TME, while IL-6 secreted by TME-related cells plays a pivotal role in tumor growth." (PMID 36104733, 2022). "Furthermore, FAP+ CAFs are considered the principal source of CXCL12 and IL-6, which have been implicated in the prevention of T cell accumulation/activity in the tumor." (PMID 36627901, 2022).
tumor (continued). "Both hypoxia and IL-6 are able to transform non-stem cancer cells into cancer stem cells, and the intrinsic radioresistance of tumor stem cells may further explain the observed association between tumor hypoxia, IL-6 levels, and patient outcomes." (PMID 34773163, 2022). "Indeed, treatment of IL-9 knockout mice with hyperIL-6 abrogated the protective effects of IL-9 deficiency and led to a marked tumour growth, thereby demonstrating that IL-9 is an important regulator of IL-6 trans-signalling effects in colorectal neoplasias." (PMID 35793807, 2022). "Altogether, these data demonstrate that KRAS mutations may drive an anti-inflammatory and pro-tumor immune suppressive microenvironment mediated through IL-6 secretion." (PMID 35159208, 2022). "Similarly, the mechanism of anticancer potential is plausibly mediated through upregulation of STAT1 gene (tumor suppressor), and downregulation of IL-6, TNF-α, and CD40 (tumor causing genes) besides other intricate mechanisms." (PMID 36612248, 2022). "MM TME is characterized by the presence of several immunosuppressive cellular and non-cellular elements including myeloid-derived suppressor cells (MDSCs), tumor-associated M2-like macrophages, regulatory T-cells, and tumor promoting and immunomodulatory factors such as IL-6, TGF-β, IL-10, PGE2." (PMID 36142133, 2022). "The interleukin-6 (IL6) gene encodes an inflammation cytokine and may be involved in key steps of tumor proliferation, apoptosis, angiogenesis, and differentiation." (PMID 35860595, 2022). "Thus, elevated serum IL6 and TNFα levels were found associated with tumor recurrence in NSCLC patients." (PMID 35688943, 2022). "Studies have also shown that IL-6 is known to have a direct effect on both tumor cells and tumor inflammatory microenvironment, and is associated with several tumor types, including lymphoma, mesothelioma, lung, breast, pancreatic, colon, prostate, and stomach cancer." (PMID 35558079, 2022). "IL-6 is associated with a back-and-forth cycle between tumor elimination and tumor promotion." (PMID 36544764, 2022). "In vitro studies have also revealed IL-6 released by CAFs causes endothelial cell migration, which could result in increased vasculogenesis and angiogenesis to facilitate increased tumor growth and dissemination." (PMID 36671452, 2022). "It is reported that the iNOS, MCP-1,and IL-6 secreted by M1 condition medium MSCs could polarize the infiltrating tumor-associated macrophages (TAM) into M2 macrophages, thereby causing immunosuppression and promoting tumor development." (PMID 36439438, 2022). "Whereas IL-6 was associated with albumin values and had a tendency to be higher in patients with worse performance status and larger tumors, IL-8 was associated with tumor diameter and partly correlated with bilirubin values." (PMID 33855585, 2022). "IL‐6 is known to be secreted from tumor cells, cancer‐associated fibroblasts, and Schwann cells." (PMID 35578571, 2022). "Notably, they established that CD8+T cell exclusion caused by CAFs was dependent on IL-6, as tumours regularly injected with IL-6 mirrored the effects of CAFs and IL-6 blockade caused a significant shift in the TIL population from FoxP3+ to CD8+ T cells." (PMID 35479076, 2022). "Thus, it was shown that MSA (3 mg/kg body weight) inhibited tumor growth up to 61% compared with the control group, and this inhibition was associated with a decrease in the level of plasma (TNFα)/interleukin 6 (IL6), and an increased level of GPXs in blood." (PMID 35216476, 2022). "Gene set enrichment analysis (GSEA) illustrated that the common enriched Hallmark sets between cells and tumours were associated with cytokine or chemokine‐related signalling pathways (such as NF‐κB and IL6/JAK/STAT3 pathway), apoptosis, and epithelial mesenchymal transition." (PMID 36116131, 2022).
tumor (continued). "Moreover, TGFβ production by tumor-infiltrating lymphocytes strongly suppresses tumor growth in colon cancer through the inhibition of the cytokine IL-6, implicated in chronic inflammation and carcinogenesis." (PMID 36497429, 2022). "mTOR is a known autophagy suppressor, so releasing this repressive effect could explain the high autophagic activity described in CAFs, which mediates paracrine secretion of tumor-promoting cytokines IL-6 and IL-8, associated with therapeutic resistance." (PMID 35159370, 2022). "IL6-induced STAT3 deregulation is associated with tumor progression in various cancers." (PMID 35264191, 2022). "We next investigate the tumor-infiltrating immune cells population (time point analyzed - D21) to determine the immunological mechanism behind the tumor rejection outcome obtained in IL-6 deficient mice by our therapeutic approach." (PMID 36405719, 2022). "Moreover, cancer-associated cells, via the secreted factors (IL-6), influence the immune response towards a pro-tumor phenotype, attracting pro-tumorigenic immune cell infiltrate (M2 macrophage, Th2 cells, Tregs, etc.)." (PMID 35328635, 2022). "More importantly, we confirmed that higher baseline levels of IL-6, whether in plasma or tumor tissues, were associated with an inferior response to ICIs in patients with NSCLC." (PMID 35550592, 2022). "Additional molecular biomarkers identified throughout the inflammatory microenvironment of VS that may contribute toward tumor-induced hearing loss include tumor necrosis factor alpha (TNFα), IL-6, CXCR4, and nuclear factor kappa-B (NFκB) activation." (PMID 35372070, 2022). "Tumour-associated myeloid cells, in particular KCs, were identified as major source for IL-6." (PMID 34047814, 2021). "IL-6 is a cytokine that produces a broad range of cellular (macrophages and fibroblasts) and physiological responses upon activation, and that has been implicated in the tumorigenesis and tumor migration of epithelial cancer." (PMID 33460401, 2021). "Finally, our results confirm EOC-associated ascites as an inflammatory tumor environment characterized by the presence of IL-6." (PMID 34359872, 2021). "Redundant amounts of IL-6 are also produced by tumor-associated exhausted CD8+ T lymphocytes." (PMID 34001144, 2021). "In that study, it was proposed that tumor-associated macrophages constitute a supportive niche by enabling pre-existing CSCs to maintain their residence in the stem cell state, through Ephrin-dependent expression of the cytokines IL6 and IL814." (PMID 34911937, 2021). "All these implicated that the anti-tumor effect of MSA was at least partly dependent on IL-6." (PMID 34393797, 2021). "Specifically, interleukin-6 (IL-6) has been associated with tumor growth and angiogenesis." (PMID 34899179, 2021). "Furthermore, other proinflammatory cytokines such as IL-6 were found to be released by Kupffer cells influenced by tumour-derived EVs and in association with liver metastasis of colorectal cancer." (PMID 35006432, 2021). "Moreover, activation of the androgen receptor by IL-6 in some subtypes of PC is associated with increased growth of tumor cells in vitro and in vivo." (PMID 34868907, 2021). "Growth inhibition of IL-6-deficient osteosarcoma cell lines in wild type mice is accompanied by NK T-cell infiltration, further supporting a role for these cells in host-dependent tumor suppression in vivo." (PMID 34079557, 2021). "When comparing the dose–response on the high expression cell line, both affinity variants have a similar potency for tumor lysis whereas the high-affinity compound has an eightfold higher potency for IL6 release associated with an approximately twofold higher maximum release (higher Emax)." (PMID 34862519, 2021). "Additionally, factors such as interleukin 6 (IL-6) and prostaglandin E2 released by the tumor cells stimulate aromatase expression in BRCA1-mutated stromal adipose cells which further enhances estrogen dependent growth of these tumor cells." (PMID 35008272, 2021).